INS (insulin)
Diseases named in the same sentence as INS in open-access papers (continued):
Sharing a sentence is not in itself a finding about the gene and the disease.
Obesity (continued). "In our study the results were not different; pregnant women with overweight or obesity showed more hypertension and hyperglycemic disorders, and insulin levels were positively correlated with prepregnancy BMI, gestational BMI, and hyperglycemia." (PMID 27651836, 2016). "The identification of the link between VitB6 and metabolic syndrome including insulin and NAFLD might help to define novel nutritional and pharmacological approaches for the treatment of diabetes, obesity, and insulin resistance." (PMID 26881239, 2016). "Adipogenesis and insulin sensitivity in obesity are also reported to be regulated by retinoid-related orphan receptor γ (RORγ) through its target gene MMP3 (matrix metalloproteinase-3 gene), which controls adipocyte size and insulin resistance in obesity." (PMID 28231175, 2016). "We found that while the prevalence of high salivary glucose and insulin concentrations both increased with obesity, they did not increase proportionally." (PMID 27069678, 2016). "SCID mice were insulin resistant in the absence of obesity and were, in fact, leaner than their counterparts." (PMID 27026807, 2016). "Together, the phenotype observed in aging mice and in mice with diet-induced obesity suggests that lack of NHA2 causes glucose intolerance, at least partially, due to inappropriate insulin secretion." (PMID 27685945, 2016). "Among those without ketonuria, the prevalence of obesity and metabolic syndrome was significantly higher and cholesterol levels, insulin levels and body mass index (BMI) were more likely to be abnormal." (PMID 27633987, 2016). "In our study, obesity was not independent predictor for insulin therapy, even though it exhibited a significant difference between AIT and MNT groups." (PMID 27478440, 2016). "However, chronic oversupply of fat to the liver, such as in obesity, leads to hepatic steatosis, increased VLDL-triacylglycerol production, hepatic insulin resistance and ultimately hepatic failure." (PMID 27591854, 2016). "Therefore, further in-depth studies are needed to clarify the in vivo anti-obesity effect of KIOM2012H on FFA uptake, energy expenditure, fat mass, insulin sensitivity, and so on." (PMID 25849950, 2015). "In childhood, the negative impact of obesity on myocardial function and on cardiac autonomic control is likely influenced by insulin resistance." (PMID 25906397, 2015). "Taken together, the protection from HFD-induced obesity led to enhanced glucose tolerance and insulin sensitivity in female DJ-1 KO mice without changes in insulin signalling in the skeletal muscle." (PMID 26077864, 2015). "TgMito MsrA, but not TgCyto MsrA, mice remain insulin sensitive after high fat feeding, though these mice are not protected from obesity." (PMID 26448611, 2015). "NEFA composition also varied with overweight/obesity and with body fat distribution, but not with insulin sensitivity." (PMID 26011768, 2015). "Our data suggest that 14-3-3ζ overexpression exacerbates age-related and diet-induced obesity, independent of changes in glucose tolerance, insulin sensitivity or lipid profile." (PMID 26220403, 2015). "Its main characteristics include fasting hyperglycemia and impaired insulin secretion in response to glucose together with a variable rate of insulin peripheral resistance in the absence of obesity." (PMID 26236746, 2015). "Some studies have reported that DAG content in skeletal muscle is not elevated during obesity, with IR, or in obese IR compared with insulin-sensitive obese subjects." (PMID 26942223, 2015). "In order to test the hypothesis that DEHP may impair insulin sensitivity, we exposed obesity resistant 129S6 mice to 2% DEHP for 10 weeks and assessed whole body insulin sensitivity and serum metabolomics." (PMID 26630026, 2015). "Offspring from insulin resistant females, but not insulin sensitive females, developed significant hepatic steatosis despite consuming a healthy diet after weaning and in the absence of obesity." (PMID 26090409, 2015).
Obesity (continued). "Naturally occurring deletion of the Nnt in the C57BL/6J mouse strain has been associated with impaired glucose homeostasis control and reduced insulin secretion that is independent of obesity." (PMID 26475342, 2015). "T2D develops when pancreatic beta cells can no longer produce enough insulin to compensate for the insulin resistance imposed by increasing obesity." (PMID 25774817, 2015). "Other researchers also observed higher insulin levels, at fasting state and after a meal intake in people with obesity, also with a lack of significant differences in glucose levels." (PMID 26609520, 2015). "In PVAT and vessels obtained from subcutaneous adipose tissue of lean humans, PVAT shows an anticontractile effect ex vivo in the absence of insulin, which is lost in obesity, and can be restored by bariatric surgery." (PMID 26003324, 2015). "The Bbs1M390R/M390R MEF cells indicate the innate cellular response to insulin because they have never been exposed to either obesity or calorie-restriction." (PMID 26103456, 2015). "Moreover, serum insulin is found to exhibit a significant positive correlation with BMI and leptin in both AMI and control subjects thereby suggesting that hyperleptinemia might be associated with the development of obesity and subsequent metabolic abnormalities such as hyperinsulinemia." (PMID 25762868, 2015). "As a first suggestion, obesity accumulated by fat impaired the insulin metabolism or insulin secretion, independent of BP in obese girls." (PMID 25768006, 2015). "In conclusion, the characteristics of combined obesity, impaired glucose tolerance and hypercholesterolemia in the DIO-hamster make this animal model useful for preclinical evaluation of novel anti-obesity, insulin sensitizing, and lipid modulating agents." (PMID 26266945, 2015). "We showed increases in non-fasting C peptide, a marker of insulin secretion, only with the largest doses, that were independent of age and degree of obesity." (PMID 26095242, 2015). "The role that elevated or dysregulated insulin/IGF signaling, like that seen with obesity and other conditions, may play in the development of cancer will be discussed further below." (PMID 26029167, 2015). "It should be pointed out that the prevalence of obesity was much underestimated in either the ever-users or never-users of insulin by using a diagnosis of obesity as a surrogate." (PMID 26537234, 2015). "The absence of TNF-α results in significantly improved insulin sensitivity in both diet-induced and ob/ob model of obesity." (PMID 26339623, 2015). "CNTF, an anti-obesity, anti-diabetogenic cytokine, promotes the same effects in mice: reduced IDE expression in the liver, reduced insulin clearance, and improved insulin sensitivity through IR-AKT phosphorylation." (PMID 25822220, 2015). "These advantages of the current model in the context of the data presented here, suggest that activation of adaptive immune cells does not influence VAT inflammation or insulin sensitivity under conditions of obesity." (PMID 26317499, 2015). "Drugs that increase insulin sensitivity such as Metformin or TZDs have no or minimal effects on lipid profile in obesity." (PMID 26157708, 2015). "For the calculated indices of glucose metabolism the approximate differences per standard deviation increase in obesity measure were a 30% lower HOMA-S, a 20% lower Gutt’s index of insulin sensitivity, and a 100 unit higher Stumvoll’s index of beta-cell function." (PMID 25849815, 2015). "Insulin is known to suppress lipolysis and stimulate lipogenesis in white adipose tissue (WAT), and mouse models with reduced adipose tissue insulin signalling are protected against obesity." (PMID 26155745, 2015). "These agents, which likely exert only modest inhibitory effects on insulin/IGFR activity, may provide a promising and safe approach, especially if effective combinations can be identified, for breaking the obesity-cancer link." (PMID 26029167, 2015).
Obesity (continued). "In this otherwise-healthy population, with some overweight but not severe obesity, insulin seems to capture an earlier stage of cardiometabolic disorders than HbA1c and glucose." (PMID 26241903, 2015). "While SA had higher fat mass and lower insulin sensitivity compared to EU, IMCL did not relate to obesity or insulin sensitivity in SA9." (PMID 26455502, 2015). "Insulin and TNF-α levels are known to be elevated during obesity in humans and rodents." (PMID 25333972, 2014). "The hyperphagia-induced model of obesity has been used by several workers in the past, including ourselves and is characterized by moderate weight gain, increased serum insulin, triglyceride and free fatty acid (data not shown) levels." (PMID 25197961, 2014). "Insulin secretion anomalies were far more frequent but interestingly were not related to the severity of obesity but rather to the subject’s age, which isn’t in total accordance with published data." (PMID 25220473, 2014). "Interestingly, it has been reported that HFD and obesity induce ER stress in the liver, which suppresses insulin signaling via JNK activation, establishing a potential link between obesity and IR." (PMID 25093191, 2014). "Schwartz reported that “it now appears that most, if not all, obesity-related AN, as well as syndromic AN, is related to insulin-resistant states”." (PMID 25031628, 2014). "RhGH treatment improved dyslipidemia, hypertension and obesity in many, but not all studies, and insulin sensitivity decreased in some studies." (PMID 24608862, 2014). "We review evidence that the AMIS (Absence of Meal-induced Insulin Sensitization) syndrome describes a paradigm fundamental to development of obesity." (PMID 26237598, 2014). "IR and fasting insulin has also been shown not to be associated with LVH in healthy people, independent of obesity." (PMID 24705608, 2014). "MSG induces hyperinsulinemia in 3-month-old rats; the obesity of MSG animals is a metabolic alteration characterized by an enhanced adipocyte capacity to transport glucose and to synthetize lipids resulting in increased insulin sensitivity." (PMID 24410812, 2014). "In contrast, although glycemia/insulin sensitivity related disease parameters (glucose, insulin, QUICKI) and obesity (body weight, epididymal fat weight) are fully resolved by T0901317 and partly by fenofibrate, no co-expression module correlated with these parameters." (PMID 25204982, 2014). "Nevertheless, in the early stage of obesity when insulin sensitivity is not impaired, this is compensated by the up-regulation of endothelium-derived hyperpolarizing factor (EDHF)-mediated vasorelaxation." (PMID 24475175, 2014). "Lifestyle change in terms of increased physical activity and exercise is the best nonpharmacological treatment for obesity since these can reduce insulin resistance, counteract the inflammatory state, and improve the lipid profile." (PMID 24563869, 2014). "The association of muscle myostatin mRNA (but not plasma myostatin) with impaired insulin sensitivity, increased triglyceride, and obesity was observed only in the healthy controls, but not in type 2 DM patients." (PMID 25254550, 2014). "Insulin and TNF-α, those are augmented in obesity, increased Oip5 mRNA level, suggesting that such obesity-related signals increase the number of preadipocytes partly through Oip5 and provide new adipocytes for fat storage to maintain energy balance in a whole body." (PMID 24516558, 2014). "Previous rat studies have shown that maternal undernutrition during pregnancy led to insulin hyper-secretion and obesity in offspring, but not to systemic insulin resistance." (PMID 25352910, 2014). "Supporting the role of BCAAs in obesity, the knock-out of the BCATm gene seems to increase BCAA levels (as seen in obesity); however, mice are surprisingly protected against HFD-induced obesity and have better glucose and insulin tolerance." (PMID 25257998, 2014).
Obesity (continued). "Individuals with GH insensitivity syndrome due to a range of GH receptor mutations are also reported to be obese and GH receptor knockout mice are insulin sensitive despite obesity and have an increase in subcutaneous fat mass and not hepatic fat." (PMID 26237614, 2014). "Skeletal muscle damage by iron overload is also responsible for diminished insulin-mediated glucose disposal, independent of obesity." (PMID 24587226, 2014). "Furthermore, deleting molecules commonly shared by many crucial signaling pathways, especially insulin signaling, could have potentially deleterious effects on overall cellular signaling cascades, which makes it difficult to delineate those factors that specifically contribute to obesity and T2DM." (PMID 24809394, 2014). "In conclusion, apelin-12 levels are significantly higher in obese female children in China compared to non-obese and correlate significantly with the obesity-related markers insulin, HOMA-IR and TG in this population." (PMID 24475149, 2014). "In our mouse model of maternal undernutrition, however, we generate mice exhibiting an opposite phenotype (resistance to diet-induced-obesity, no insulin resistance)." (PMID 25118945, 2014). "However as obesity advances and T2DM develops in response to a reversible or irreversible downturn in insulin secretion, the activation of hepatic IRS-1/PI3K, and thus of hepatic Akt, diminishes." (PMID 26237474, 2014). "In obesity, this effect of insulin is absent suggesting the existence of additional mechanism of pathogenic interplay between insulin resistance and atherothrombosis." (PMID 25601838, 2014). "It is speculated that ghrelin, which is decreased in simple obesity but increased in PWS, might play a role in blocking the inhibitory effect of insulin on IGFBP-1 production." (PMID 26237614, 2014). "Apelin-12 levels are significantly higher in obese vs. non-obese girls in China and correlate significantly with obesity-related markers insulin, HOMA-IR, and TG." (PMID 24475149, 2014). "Further, smokers had lower levels of insulin and glucose than nonsmokers, independent of obesity measures such as BMI or waist circumference." (PMID 24789040, 2014). "In previous studies, pathophysiological factors such as obesity, FBG, TG, HDL, hypertension, metabolism syndrome, insulin, and peripheral neuropathy were all thought of as possible risk factors for the high prevalence of the typical GERD symptoms in DM patients." (PMID 25530757, 2014). "Overweight or obesity was observed in 978 patients (31.6%), and weight status was not statistically related with the type of insulin regimen." (PMID 24920963, 2014). "Differing from the TSNO mouse that does not become obese, the TSOD mouse exhibits polygenic obesity and insulin resistant at about 2 months old, which results in hyperinsulinemia and hyperglycemia, but just in males." (PMID 23671868, 2013). "Of note, mice which only lack SCD1 in liver and thus have normal skin barrier function were not resistant to high-fat diet-induced obesity, but still exhibited improved insulin sensitivity." (PMID 23760815, 2013). "Obesity not only leads to excessive fat storage in adipose tissue, but also to ectopic fat storage in other insulin sensitive tissues such as the muscle and liver (nonalcoholic fatty liver disease; NAFLD)." (PMID 23781256, 2013). "Furthermore, in diet-induced obesity in mice, FGF-21 is enhancing insulin-mediated suppression of endogenous glucose production and enhancing insulin-mediated glucose uptake in skeletal muscle." (PMID 23533568, 2013). "Adiponectin for example, an anti-inflammatory adipokine, which is reduced in obesity and T2DM, has been shown to increase insulin sensitivity and to improve vascular function by reducing TNF-α-stimulated expression of endothelial adhesion molecules and monocyte attachment." (PMID 24369540, 2013).
Obesity (continued). "This occurred without causing significant body weight gain or obesity, and the metabolic effects of HFD on blood glucose and insulin levels were modest." (PMID 24156623, 2013). "On the other hand, mice that lack PPARγ specifically within the CNS are resistant to dietary-induced obesity and do not increase feeding or show improvements in hepatic insulin sensitivity when administered PPARγ agonists." (PMID 23550218, 2013). "The data regarding cortisol are in agreement with the study of Weigensberg and coworkers who demonstrated that cortisol is higher in obese Latino youths with MetS, independent of the degree of obesity and insulin sensitivity." (PMID 23425018, 2013). "This indicates that adipose tissue-derived human SAA1 does not have proinflammatory properties and does not affect obesity-related inflammation or insulin sensitivity in mice." (PMID 23967285, 2013). "Without the inflammatory component, obesity does not lead to appreciably impaired insulin action as demonstrated in macrophage-specific IKKβ and JNK1-KO mice." (PMID 23577240, 2013). "The old rats presented high levels of insulin, which is considered one of the main characteristics of obesity, with no change in glucose levels on fasting condition." (PMID 23442260, 2013). "Ablation of FABP5 led to a mild increase in systemic insulin sensitivity in genetic and dietary obesity mouse models, whereas adipose tissue-specific overexpression of FABP5 in transgenic mice resulted in a reduction in systemic insulin sensitivity in a high-fat diet model." (PMID 24278421, 2013). "Further, significant higher level of leptin was found in insulin resistant subjects compared to the subjects without the condition at the same level of obesity in both gender." (PMID 23349940, 2013). "Lean, formerly overweight (obesity-prone) AA women were more insulin sensitive than their never overweight counterparts." (PMID 23298367, 2013). "Descriptive statistics of all study participant serum samples tested for Bone Panel (osteoprotegrin (OPG), leptin, parathyroid hormone (PTH) and insulin), Matrix Metalloproteinase Panel (MMP-2, MMP-8, MMP-9) and Obesity Panel (adiponectin and C-reactive protein (CRP))." (PMID 23577067, 2013). "Obesity and deposition of lipid in visceral adipose tissue does not occur, likewise insulin resistance does not develop." (PMID 23762326, 2013). "Indeed, elevated insulin level and impaired insulin sensitivity were detected in the young lean MC4R knockout mice, even before the development of pronounced hyperphagia and obesity." (PMID 24191197, 2013). "Sleep apnea is also linked with the risk of incident hypertension, metabolic syndrome and with lower insulin sensitivity independent of obesity." (PMID 23951064, 2013). "However, there are a number of diet alterations that can also modify obesity-related signals, specifically, GSE, silibinin, probiotics, and EGCG have all been shown to beneficially modify insulin signaling." (PMID 23675573, 2013). "In this study, it was found that the modified diet did not have any influence on insulin, nitric oxide levels, or obesity index within 6 weeks, but that excess iron in the modified diet caused significant decreases in these metabolic parameters." (PMID 23179349, 2013). "In this study, neither the concentration of nitric oxide nor the serum insulin level or obesity index was affected by the high fat, fructose, or salt diet." (PMID 23179349, 2013). "In conclusion, rosuvastatin improves glucose intolerance, insulin sensitivity and NAFLD in a dose-dependent manner and changes the fat distribution from visceral to subcutaneous fat depot in a mouse model of diet-induced obesity." (PMID 23816341, 2013). "Taken together, these data indicate that overactivated JNK signaling in skeletal muscle as present during the course of obesity fails to impair whole body glucose homeostasis and insulin-stimulated signaling events in vivo." (PMID 23349837, 2013).